SAMMSON (survival associated mitochondrial melanoma specific oncogenic non-coding RNA)
Diseases named in the same sentence as SAMMSON in open-access papers (continued):
Sharing a sentence is not in itself a finding about the gene and the disease.
conjunctival melanoma (1 paper, 2022). "SAMMSON expression was also detected in the conjunctival melanoma (CM) cell lines CRMM1 and CRMM2 that are genetically and phenotypically more related to skin melanoma." (PMID 34508176, 2022). "In this study, we show that SAMMSON is consistently expressed in UM and conjunctival melanoma (CM) cells, the latter of which are phenotypically and genetically more related to skin melanoma." (PMID 34508176, 2022). "In addition, SAMMSON expression could be observed in conjunctival melanoma (CM) cells that are genetically and phenotypically more related to skin melanoma." (PMID 34508176, 2022).
gastric cancer (1 paper, 2023). A primary or metastatic malignant neoplasm involving the stomach. "SAMMSON expression is also closely related to survival time and clinical stage in gastric cancer." (PMID 36869839, 2023).
glioma (1 paper, 2022). A benign or malignant brain and spinal cord tumor that arises from glial cells (astrocytes, oligodendrocytes, ependymal cells). "Some, SOX2-OT, ZFAS1, SAMMSON, CASC19/PCAT2, and PVT1, have already been associated with various cancers, including gliomas." (PMID 35852875, 2022).
metastatic tumors (1 paper, 2022). "Since SAMMSON expression levels are elevated in metastatic tumors, these results highlight the broad relevance of SAMMSON inhibition as a potential therapeutic strategy, which may be primarily of interest for metastatic UM patients, where the therapeutic need is high." (PMID 34508176, 2022).
skin melanoma (1 paper, 2022). "Recently, Survival Associated Mitochondrial Melanoma Specific Oncogenic Non-coding RNA (SAMMSON) was discovered on chromosome 3p13 as a lineage survival oncogene in skin melanoma." (PMID 34508176, 2022). "Our work demonstrates that, similar to skin melanoma, ASO-mediated SAMMSON knockdown in various in vitro and in vivo UM models induces a potent anti-tumor response including growth reduction, induction of apoptosis, and reduced levels of tumor-derived DNA in lung tissue." (PMID 34508176, 2022).
triple-negative breast carcinoma (1 paper, 2023). An invasive breast carcinoma which is negative for expression of estrogen receptor (ER), progesterone receptor (PR), and human epidermal growth factor receptor 2 (HER2).
cancer (15 papers, 2017 to 2024). A tumor composed of atypical neoplastic, often pleomorphic cells that invade other tissues. "SAMMSON is considered a potential diagnostic and prognostic biomarker in several types of cancer and a suitable therapeutic target." (PMID 37772815, 2023). "Investigation of the function of SAMMSON as a diagnostic and prognostic value in different cancers has been the subject of a few studies." (PMID 37772815, 2023). "The expression of SAMMSON detected in different types of samples, including tissue, blood, plasma and cell lines; therefore, SAMMSON can be considered a non‐invasive potential diagnostic and prognostic biomarker in several types of cancers and a suitable therapeutic target for various tumours." (PMID 37772815, 2023). "In addition, the highly expressed SAMMSON is closely associated with clinicopathological features of various cancers." (PMID 37772815, 2023). "Thus, both RMRP and SAMMSON are mitochondrial metabolic regulators with recurrent SCNAs due to focal amplifications, causally involved in cancer." (PMID 33329688, 2020). "It exhibits up-regulated expressions of the cancer-associated lncRNAs FOXCUT, SAMMSON, ENSG00000251320, and ENSG00000248927, as well as ion channels in nerve fibers, such as GRIA2 and GABARR1." (PMID 37445678, 2023). "In uveal melanoma (UM) (the most common eye tumour in adults), the expression level of SAMMSON was upregulated in tissues and cancer cell lines." (PMID 37772815, 2023). "In some other studies, SAMMSON was identified as a key lncRNA in the progression of malignant tumors." (PMID 36620596, 2022). "Comparing with non-cancer tissues, significantly lower expression levels of SAMMSON were observed in HCC tissues (P<0.05)." (PMID 31164410, 2019). "In the following, the role of SAMMSON in various cancers is examined in more detail." (PMID 37772815, 2023). "In this study, we hypothesize that, due to its important role in metabolic orientation, SAMMSON could be a key player in cancer progression and chemotherapies resistance, two situations exploiting the metabolic vulnerability of the cells." (PMID 34827149, 2021). "Therefore, SAMMSON negatively regulated miR-9-3p in HCC cells to promote cancer cell migration and invasion." (PMID 31164410, 2019). "The expression of SAMMSON in OSCC was found to be significantly higher in tissue samples, plasma samples, and OSCC cancer cell lines." (PMID 37772815, 2023). "In particular, the cancer-related lncRNA, such as SAMMSON and FOXCUT, belong to the gene network with the cancer-related transcription factor FOXC1." (PMID 37445678, 2023). "ExInAtor was modeled on 1112 whole genomes from 23 cancer types deposited in GENCODE, and predicted 15 lncRNA drivers with a high confidence, of which nine were novel lncRNAs and six were known cancer-related transcripts, including PCA3, MALAT1, BCAR4, lncRNA-ATB, and SAMMSON." (PMID 38068923, 2023). "In OSCC, SAMMSON expression was found to be elevated and correlated with OSCC stage, suggesting it may play an important role in this type of cancer." (PMID 36869839, 2023). "In non-cancer tissues, SAMMSON and miR-9-3p were not significantly correlated." (PMID 31164410, 2019).
tumor (9 papers, 2019 to 2025). "Co-amplified with MITF and transcriptionally linked to the melanocytic lineage programme, SAMMSON sustains the bioenergetic and biosynthetic capacity of tumour cells by directly coordinating mitochondrial translation and integrity." (PMID 41463281, 2025). "LncRNAs, including ANRIL, HOTAIR, MALAT1, SAMMSON, etc., have been implicated to play an essential part in tumor progression, metastasis, and anti-tumor immunity in melanoma via numerous research." (PMID 37770477, 2023). "The overexpression of SAMMSON can promote tumour progression by increasing cell proliferation, invasion, migration, epithelial‐mesenchymal transition (EMT), chemoresistance, and apoptosis suppression." (PMID 37772815, 2023). "To investigate the mechanism by which SAMMSON contributes to UM tumor cell survival, we studied SAMMSON interaction partners in UM cell lines." (PMID 34508176, 2022). "Its interaction with CARF via SAMMSON promotes its mitochondrial targeting, where it increases protein synthesis, leading to an increased tumor cell growth." (PMID 32180794, 2020). "The role of this lncRNA in melanoma has promising therapeutic implications since the combination of inhibitors of both BRAF and SAMMSON in pre-clinical models apparently exert a synergistic anti-tumor effect." (PMID 31861757, 2019). "The most relevant activity of SAMMSON is the activation of the mitochondrial p32 protein, which is a critical regulator of tumor metabolism via maintenance of oxidative phosphorylation and mitochondrial homeostasis." (PMID 31861757, 2019). "Preclinical studies have demonstrated that silencing of MALAT1, HOTAIR, or SAMMSON using antisense oligonucleotides (ASOs) or gapmeRs dramatically reduces intratumoral vessel density and tumour growth and shows synergistic effects with BRAF/MEK inhibitors and bevacizumab." (PMID 41463281, 2025). "Also, SAMMSON plays a crucial role in tumour growth by affecting different aspects of mitochondrial metabolism." (PMID 37772815, 2023). "Moreover, a recent annotated lncRNA SAMMSON is regulated by melanocytic-specific transcriptional factor SOX10, and the deficiency of SAMMSON is capable of restraining tumor progression and increasing the efficacy of MAPK-inhibition targeted therapy." (PMID 35693795, 2022). "Our in vitro data, based on multiple cell lines with a different genetic background, and in vivo data, based on two genetically different UM PDX models, suggest that the genetic background of the tumor does not influence the response to SAMMSON inhibition." (PMID 34508176, 2022).
SAMMSON also shares sentences with these, for which no sentence is quoted: autoimmune disease (1 paper); intracranial aneurysms (1); liver cancer (1); lymph node metastasis (1); metastasis (1); multiple myeloma (1); oral squamous cell carcinoma (1); thyroid cancer (1).